RNASE8 (ribonuclease A family member 8)
Description:
Has a low ribonuclease activity.
Synonyms: RAE2
Tractability: Antibody: UniProt places it where antibodies can reach, with high confidence; UniProt predicts a signal peptide or a membrane-spanning region; its Gene Ontology location is reachable by antibodies, with medium confidence.
Gene: Protein-coding gene on chromosome 14 (21,057,822 to 21,058,455, forward strand). Ensembl gene ENSG00000173431.
Subcellular location: Secreted
Pathways (Reactome):
Immune System: Antimicrobial peptides
Gene Ontology:
Molecular function: ribonuclease A activity; RNA nuclease activity; nucleic acid binding
Biological process: antifungal innate immune response; defense response to Gram-negative bacterium; defense response to Gram-positive bacterium; innate immune response; defense response to fungus
Cellular component: extracellular region
Genetic constraint (gnomAD): Loss-of-function variants: 0 observed, 0.64 expected, observed/expected ratio (o/e) 0, 90% interval 0 to 1.81. That is too few expected variants to judge how well the gene tolerates losing a copy. Missense variants: 179 observed, 197.6 expected, observed/expected ratio (o/e) 0.91, 90% interval 0.8 to 1.02. Synonymous variants: 68 observed, 78.84 expected, observed/expected ratio (o/e) 0.86, 90% interval 0.71 to 1.05.
Homologues: Orthologues: chimpanzee RNASE8 (97% identical). Paralogues in human: RNASE7 (78% identical), RNASE6 (52% identical), RNASE2 (44% identical), RNASE3 (40% identical), RNASE1 (36% identical), RNASE4 (34% identical), ANG (25% identical), RNASE10 (23% identical), RNASE13 (20% identical), RNASE9 (20% identical), RNASE12 (19% identical), RNASE11 (16% identical).